XBP1 (X-box binding protein 1)
Diseases named in the same sentence as XBP1 in open-access papers (continued):
Sharing a sentence is not in itself a finding about the gene and the disease.
melanoma (continued). "To investigate the splicing level of XBP1 in melanoma cells, we analyzed mRNA levels of the spliced form of XBP1 (XBP1s) in a group of cell lines containing normal melanocytes (HEMn-MP and HEMn-DP) and melanoma cells (Mel-RMu, MM200, Mel-CV, IgR3, A2058 and SkMel-28)." (PMID 28222747, 2017). "Another study suggested that elevated cholesterol levels in B16 melanoma trigger ER stress in CD8+ T cells, activating XBP1, which then upregulates PD1; this promotes cancer progression by depleting CD8+ T cells within the TME." (PMID 40035165, 2025). "The ITRGM signature includes GBP5, HLA-DPB1, XBP1, CD40, CXCL10, and TNFSF13B, each playing pivotal roles in the immune response and tumor microenvironment of melanoma." (PMID 39355255, 2024). "We previously proved that SIRT7 selectively activated the IRE1α-XBP1 axis to simultaneously regulate downstream ERK signal and secretion of cytokines, thus enabling melanoma cell survival under ER stress." (PMID 36918544, 2023). "The IRE1α-XBP1 pathway suppresses expression of NKG2D, thus attenuating NK cell-driven anti-tumor toxicity in melanoma cell lines." (PMID 37769655, 2023). "In agreement with results from previous studies, the magnitude of nascent protein production was found to be higher in the melanoma cell lines than in the melanocytes, thus potentially leading to the activation of UPR pathways, including the IRE1α-XBP1 branch." (PMID 28222747, 2017). "The magnitude of the nascent protein production is higher in melanoma cell lines and results in the activation of UPR pathways, including the IRE1α-XBP1 branch." (PMID 28222747, 2017). "It is worth noting, however, that overexpression of XBP1 in BMDC actually improves DC survival, activation, and T cell stimulatory capacity, leading to enhanced immune control of established B16 melanoma following vaccination." (PMID 29209327, 2017). "Consistent with our in vitro findings, genes associated with the ATF4 (e.g., ATF4, DDIT3, PPP1R15A and CHAC1), ATF6 (e.g., ATF6B, CALR, SEL1L, and EDEM1) and XBP1 (e.g., SSR3 and DELR1) pathways were significantly enriched in melanoma TILs compared with healthy blood T cells." (PMID 40335738, 2025). "STF083010, an IRE1α RNase inhibitor, could impair PD1 expression in CD8+ T cells by inhibiting the transcriptional activity of XBP1 and enhancing the antitumour immunity of CD8+ T cells in mouse models of melanoma." (PMID 38297380, 2024). "XBP1, a transcription factor regulating MHC class II expression, has dual roles in melanoma—potentially enhancing anti-tumor immunity through dendritic cells and NK cells, while also exhibiting immunosuppressive properties in melanoma." (PMID 39355255, 2024). "Therefore, apart from the reports that NF-κB could be regulated by IRE1α-XBP1 axis that is dependent on the endonuclease activity of IRE1α, IRE1α might also participate in the regulation of NF-κB directly via its kinase activity in melanoma cells undergoing ER stress." (PMID 38291473, 2024). "Melanoma cells were treated for one hour with different concentrations of amitriptyline, leading to activation of PERK and IRE1 signaling as measured by phosphorylated eIF2α and spliced XBP1, respectively." (PMID 36831408, 2023). "A modest effect is observed in mice bearing single deletion of XBP1s in DCs, which showed slight acceleration of melanoma tumor growth and dysfunctional T cell responses, however, this effect was not recapitulated in animals lacking XBP1 only in cDC1s." (PMID 37346037, 2023). "XBP1-s can also bind to the ACGT core sequence of the IL-6 promoter and enhance its transcription, leading to the activation of the STAT3 signaling pathway and enhanced tumorigenesis of melanoma, hepatocarcinoma, and primary effusion lymphoma." (PMID 35269888, 2022).
melanoma (continued). "In summary, we reported the xbp1/hsp70-driven TRP2 genetic skin immunization effectively promotes durable antitumor immunity against PD1 (and Brafi)-resistant, multifocal melanoma and that this treatment sensitizes PD1-resistant disease to corollary (re)treatment with αPD1 mAb-based immunotherapy." (PMID 33408093, 2021). "In addition, we determined the expression of stress (CHOP, XBP1, and BIP) and autophagy (DRAM1, P62, ATG5, and ATG7) marker genes; furthermore, we successfully developed an HA15-resistant melanoma cell line." (PMID 33498201, 2021). "In contrast, in melanoma cells, ER stress induces drug resistance with the activation of the phosphatidylinositol 3-kinase/protein kinase B (PI3/AKT) pathway through the X-box binding protein 1 (XBP1) protein upon treatment with microtubule-targeting drugs, docetaxel and vincristine." (PMID 31963677, 2020). "On the other hand, since EGb761 did not increase GRP78 and the cleaved form of XBP1, two commonly used marker of activation of the ER stress response, it is unlikely that EGb761 kills melanoma cell by induction of ER stress (data not shown)." (PMID 25860257, 2015). "In conditional knockout mouse models with NK cell-specific deletion of either IRE1α or XBP1, experimental groups demonstrated significantly impaired tumor immunosurveillance compared to wild-type controls following intravenous challenge with B16F10 melanoma cells." (PMID 41209558, 2025). "Through the regulation of the miR‐526b‐3p/XBP1 signalling pathway, LINC02202 may play a role in tumour progression and immune infiltration and inhibiting the expression of LINC02202 can increase the efficacy of immunotherapy for melanoma." (PMID 38520212, 2024). "It reduces the growth of melanoma cells (A375 and B16F10) in vitro in a dose-dependent manner, induces ER stress via the inositol-requiring enzyme type 1 (IRE1)/X-box binding protein 1 (Xbp1) pathway, and prompts caspase-12/caspase-4-mediated death in both cell lines." (PMID 39371094, 2024). "In this study, both the GRP78 protein and the active form of XBP-1 mRNA, two commonly used markers of activation of the UPR, were induced by 2-DG, indicating that, consistent with its inhibitory effect on glycolysis and glycosylation, 2-DG activated the UPR in melanoma cells." (PMID 20003459, 2009). "Moreover, XBP-1, which is known to be transcriptionally regulated by ATF6 and functionally activated by IRE1α, was found to play an important role in 2-DG-mediated transcriptional up-regulation of TRAIL-R2 in melanoma cells." (PMID 20003459, 2009). "Moreover, the mRNA expressions of two critical XBP1 target genes ERDJ4 and EDEM1 were also significantly correlated with PTPRC, CD8A and IFNG, respectively, indicating the potential facilitative role of IRE1α-dependent UPR branch in anti-tumor immunity in melanoma." (PMID 38291473, 2024). "To prove that the selective activation of the IRE1α-XBP1 axis and IRE1α-dependent ERK activation accounted for the protective role of SIRT7 under stress, we employed colony formation assay by using WM35 melanoma cells with or without SIRT7 overexpression." (PMID 36918544, 2023). "In contrast, BMDC pulsing with melanoma cell lysates activated XBP1 splicing but not RIDD, and XBP1s appeared to promote, rather than disrupt, efficient melanoma antigen cross-presentation." (PMID 35446348, 2022).
ovarian carcinoma (41 papers, 2016 to 2025). A malignant neoplasm originating from the surface ovarian epithelium. "The study elegantly demonstrated that XBP1-deficient T cells enriched effector function in mouse models of ovarian cancer, providing evidence for the IRE1α axis as an immunotherapeutic target in cancer." (PMID 35573704, 2022). "In contrast, constitutive activation of XBP1 in DCs results in abnormal accumulation of lipids in tumor-associated DCs and subsequent dysfunction of antitumor T cells in ovarian cancer." (PMID 35884393, 2022). "Since mutations in BRCA1 and BRCA2 were identified as major causes of ovarian cancer, the relationship between XBP1 and BRAC1/BRAC2 was individually analyzed." (PMID 35991556, 2022). "Cubillos-Ruiz also observed that IRE1α deficiency in dendritic cells yielded greater survival than XBP1 deficiency in a model of ovarian cancer." (PMID 32520957, 2020). "Compounds that could sequester ROS or lipid peroxidation by-products (vitamin E or hydralazine, respectively) were reported to inhibit Xbp1 mRNA splicing and prevent the induction of the expression of ER stress response genes in ovarian cancer-associated DCs." (PMID 38136940, 2023). "Finally, the constitutive activation of XBP1 in tumor-associated DC drives ovarian cancer progression, whereas DC-specific XBP1 deletion restores their immunostimulatory activity, hence enabling anti-tumor T cell responses." (PMID 35237269, 2022). "Moreover, XBP1 was further observed to be closely associated with anti-tumor immunity in ovarian cancer, including multiple immune effector molecules and T-cell signatures." (PMID 35991556, 2022). "The constitutive activation of the host unfolded protein response ER stress pathway mediated by XBP-1 in ID8DV ovarian tumor associated dendritic cells was recently shown to be a central immunosuppressive mechanism that promotes ovarian cancer progression by dampening antigen presentation." (PMID 27447180, 2016). "In particular, activation of the ER stress response factor XBP1 induced by lipid peroxidation in tumour‐associated DCs (tDCs) blunts antitumour immunity by inhibiting the capacity of tDCs to support antitumour T cells and then drives ovarian cancer progression." (PMID 36639835, 2023). "In ovarian cancer, the induction of ER stress and IRE1α–XBP1 axis activation in both CD8+ T and CD4+ T cells regulate glutamine carrier levels." (PMID 40547943, 2025). "Research has shown that human ovarian cancer‐derived T cells isolated from samples exhibit extensive XBP1 splicing and increased expression of ER stress genetic markers." (PMID 40035165, 2025). "The IRE1α-XBP1 pathway modulates T cell functionality in ovarian cancer through the regulation of mitochondrial dynamics and activity, demonstrating that XBP1s is also associated with mitochondrial function and tumor immunity." (PMID 39264847, 2024). "In ovarian cancer, IRE1α-XBP1 signalling has been found to inhibit T-cell infiltration and IFNγ expression, thereby promoting tumour progression." (PMID 38297380, 2024). "In line with our results, carriers of the GWAS risk alleles exhibit an increased expression in triple-negative breast cancer (TNBC) cells, while ovarian cancer cells show a decreased XBP1 expression." (PMID 39623312, 2024). "This suggests that the IRE1α/XBP1 axis promotes expressions of stemness-related genes, promoting ovarian cancer cell stemness, and that its regulation by FOXK2 is via the IRE1α/XBP1 axis." (PMID 38711526, 2024). "Accordingly, the expression of XBP1 in CD11c+ DCs was reported to be critical for the initiation and progression of ovarian cancer, and its conditional ablation in DCs in the tumour microenvironment enhanced the capacity to restrict tumour growth." (PMID 38136940, 2023). "It has been reported that in ovarian cancer, DCs exhibit high levels of intracellular ROS and lipid peroxidation, which significantly induce IRE1α-XBP1, resulting in aberrant DC immunological function." (PMID 37067519, 2023).
ovarian carcinoma (continued). "Further bioinformatics analysis, we found that XBP1 was highly expressed in ovarian cancer, and high XBP1 expression significantly favors both overall survival and disease-free survival of patients with ovarian cancer." (PMID 35991556, 2022). "The general landscape of XBP1 and immune checkpoint alteration in ovarian cancer was compactly visualized, including amplification, deep deletion, fusion, structural variant, truncating, missense, and splice mutations." (PMID 35991556, 2022). "In ovarian cancers, ascites fluid from ovarian cancer patients prohibited glucose uptake by T cells, ultimately leading to IRE1α-XBP1 activation that repressed mitochondrial respiration." (PMID 35573704, 2022). "Together, this evidence strongly suggests that XBP1 had a significant impact on the antitumor immune response in ovarian cancer therapy." (PMID 35991556, 2022). "Using a high-throughput sequencing database, our results showed that XBP1 couples with immune checkpoints in ovarian cancer." (PMID 35991556, 2022). "Through the analysis of the cBioPortal database, we found that the genomic investigation revealed that XBP1 was actually involved in the alteration of immune checkpoints in ovarian cancer." (PMID 35991556, 2022). "More importantly, XBP1 was further observed to be closely related to anti-tumor immunity in ovarian cancer, including multiple T-cell signatures and immunity-killing molecules." (PMID 35991556, 2022). "Intriguingly, the genomic alteration of X-box binding protein 1 (XBP1), the important mediator of chemotherapy-induced cancer immunogenic cell death, was found to be a potential coregulator of immune checkpoints in ovarian cancer." (PMID 35991556, 2022). "In summary, we analyzed the importance of immune checkpoints in ovarian cancer by using publicly available gene expression data, and propose XBP1 as a more promising target for the therapy of ovarian cancer." (PMID 35991556, 2022). "Since molecular therapy has lower toxicity than chemical drugs in the long term, and adaptable to each person, we used miR-30c-2-3p to target XBP1 in ovarian cancer cells." (PMID 34121978, 2021). "In this study, we examined the effect of degradation of XBP1 by transfection of mimic miR-30c-2-3p on ovarian cancer cell lines." (PMID 34121978, 2021). "The current study demonstrates that XBP1 plays a crucial role in the ERS-induced ovarian cancer apoptosis." (PMID 34121978, 2021). "Overall, the present paper adds new evidence to the possible treatment of miR-30c-2-3p via impeding the XBP1 transcription in ovarian cancer cells provoking apoptotic pathways by XBP1/CHOP/BIM mediators." (PMID 34121978, 2021). "In ovarian cancer, the IRE1α/XBP1 axis was shown to cripple T-cell metabolism and that T cells lacking XBP1 have superior antitumor immunity, delayed malignant progression, and increased overall survival." (PMID 32520957, 2020). "Ovarian cancer tissue can induce ER stress and activate the IRE1α-XBP1 arm of T cells involved in protein expansion response, thereby controlling the mitochondrial function and antitumor ability of T cells." (PMID 33117713, 2020). "Higher level of XBP1 correlates with lower survival rate and poor prognosis of patients with glioblastoma; conversely, ovarian cancer mouse treated with XBP1-silencing nanoparticles exhibited better prognosis, as compared to control." (PMID 33276627, 2020). "This process was mediated by constitutive activation of endoplasmic reticulum (ER) stress response factor XBP1, with knock-out or silencing of XBP1 promoting survival of ovarian cancer-bearing mice." (PMID 32121071, 2020). "The study of T cells isolated from ovarian cancer patients found that up-regulation of XBP1 would reduce the ability of T cells to infiltrate tumor tissues and reduce the expression of IFNG mRNA." (PMID 33117713, 2020).
ovarian carcinoma (continued). "It is reported that XBP1 KO CD11b+ DCs infiltrating ovarian cancer tumors are more efficient to activate anti-tumor CD8+ and CD4+ T cell responses and can control tumor growth." (PMID 30687308, 2018). "Functional studies have conducted inhibitor assays in several malignant tumors, including MM, pancreatic cancer, ovarian cancer, and prostate cancer using IRE1α-XBP1 inhibitors both in vitro and in vivo." (PMID 29581854, 2018). "Conditional deletion of Xbp1 in DCs resulted in delayed ovarian cancer progression and this process was mediated through the induction of protective T cell anti-tumor immunity." (PMID 28105371, 2017). "Dendritic cell specific XBP1 deletion restored anti-tumor immune function in ovarian cancer, suggesting an immune benefit of targeting IRE1 in this immune cell subtype." (PMID 29113324, 2017). "IRE1α-XBP1 activation and overexpression of various endoplasmic reticulum (ER) stress response markers were reported in ovarian cancer-associated DCs as compared with DCs isolated from non-tumorigenic normal tissues." (PMID 38136940, 2023). "Furthermore, deletion of Xbp1 has been shown to enhance T cell effector function in the ovarian cancer microenvironment." (PMID 37874641, 2023). "This also means immune checkpoint inhibitor therapy combined with chemotherapy in XBP1-upregulated cancers might be a more appropriate therapeutic strategy for ovarian cancer and provide patients with an extra survival benefit." (PMID 35991556, 2022). "Importantly, XBP1 was detected to be highly expressed in ovarian cancer compared with normal ovarian tissue, and high XBP1 expression significantly benefits both overall survival (OS) and disease-free survival (DFS) of ovarian cancer patients." (PMID 35991556, 2022). "In the present study, the expression of the GRP78/BIP protein was mildly reduced by miR-30c-2-3p in transfected ovarian cancer cells, suggesting that the blockage of XBP1 through miR-30c-2-3p can enhance the accumulation of the mis/unfold protein and promote apoptosis." (PMID 34121978, 2021). "In addition, targeting the IRE1α-XBP1 pathway benefits T-cell function directly in the ovarian cancer microenvironment by increasing mitochondrial respiration activity and attenuating cholesterol-induced CD8+ T-cell exhaustion." (PMID 32850317, 2020). "In ovarian cancer, dysfunctional tumor-associated DCs (tDCs) showed robust expression of ER stress markers and sustained activation of the IRE1α − XBP1 arm of the UPR, compared with DCs residing in non-tumor locations." (PMID 28105371, 2017). "In preclinical ovarian cancer models, these interventions significantly delay tumor progression and improve survival outcomes, suggesting therapeutic targeting of the IRE1α-XBP1 axis in DCs could potentiate endogenous antitumor immunity and improve immunotherapy efficacy." (PMID 41209558, 2025). "For example, IRE1α-XBP1 over-activation in dendritic cells could disrupt the lipid metabolic homeostasis and cripple antigen presentation to T cells, thereby impeding the protective immune responses against tumor cells in ovarian cancer." (PMID 38291473, 2024). "Tumor-infiltrating lymphocytes were demonstrated to display an increase in XBP1 activity, which was markedly associated with dysregulated N-linked glycosylation, perturbed mitochondrial respiration, and decreased IFN-γ production in patients with ovarian cancer." (PMID 37067519, 2023). "Also, the core of triglyceride biosynthesis genes regulated by XBP1s in DCs from ovarian cancer are not found as DEG in XBP1 deficient tumor cDC1s from this study." (PMID 37346037, 2023).